BRAF (B-Raf proto-oncogene, serine/threonine kinase)
Diseases named in the same sentence as BRAF in open-access papers (continued):
Sharing a sentence is not in itself a finding about the gene and the disease.
thyroid cancer (continued). "This represents a novel mechanism in BRAF V600E-promoted PTC aggressiveness and identifies WIPF1 as a novel therapeutic target for thyroid cancer." (PMID 27863429, 2017). "Two thyroid cancer cell lines, 8505C and BCPAP were selected and treated with BRAF inhibitor, PLX4032 and its effect on EMT were examined and compared." (PMID 27880942, 2017). "Interestingly, concomitant BRAF V600E were observed in our HVPTC patient with TERT promoter mutation who died of disease during follow-up, which was consistent with the previous reports that coexistence of BRAF V600E and TERT represented the more aggressive biological behavior in thyroid cancer." (PMID 28423545, 2017). "However, Ghossein and Livolsi found that TCV is overrepresented in fluorodeoxyglucose positron-emission tomogram (FDG-PET)-positive thyroid carcinomas that are refractory to RAI therapy, which may due to a high prevalence of BRAF somatic mutations in patients with TCV." (PMID 28009980, 2017). "Altered MAPK signaling pathway in many thyroid cancers leads to ERK phosphorylation, proliferation, and invasion hence BRAF inhibitors (BRAFi) and MEK inhibitors (MEKi) have been the subject of intense investigation." (PMID 26943572, 2016). "This is consistent with the findings of previous studies showing differences between the effects of BRAF and RET/PTC alterations on gene expression in thyroid cancer." (PMID 26810418, 2016). "The current well-established detection methods for thyroid cancers are US, FNAC, and molecular analysis, which mainly consists of BRAF V600E, but each method has its own shortcomings and insufficiency." (PMID 27654865, 2016). "Many somatic genetic alterations including those in BRAF, HRAS, KRAS, NRAS, PTEN, and HER1 have been revealed to play fundamental roles in the tumorigenesis of thyroid carcinoma." (PMID 27833153, 2016). "It has been reported that the knockdown of B-RafV600E, a mutant form of the gene BRAF, resulted in TSP-1 down-regulation in human thyroid cancer cells with a significant reduction of adhesion and migration/invasion of these cells in tumors." (PMID 26461935, 2015). "The thyroid cancer progression hypothesis is corroborated by a transgenic mouse model for the early activation of the BRAFT1799A oncogene restricted to the thyroid gland (Tg-BRAF) that is affected by high penetrance PTC that undergoes temporal dedifferentiation." (PMID 25202329, 2014). "Knockdown of BRAF has been revealed to induce inhibition of the MAP kinase pathway, growth arrest and DNA damage in thyroid cancer cell lines." (PMID 25289082, 2014). "These are consistent with the similar impact of BRAF V600E on the histone acetylation of NIS promoter and expression of the NIS gene in both rat thyroid cells and human thyroid cancer cells, in this study." (PMID 24243688, 2014). "BRAFV600E mutation, which is the most common oncogenic genetic event found in thyroid cancer, particularly in PTC, results in constitutive and oncogenic activation of BRAF kinase in the MAPK signaling pathway." (PMID 24588959, 2014). "Furthermore, the V600E BRAF mutation is not specific of thyroid cancer." (PMID 23162534, 2012). "These biomarkers, such as CK19, TG, Ki67, Calcitonin, TTF-1, BRAF, RET, HBME-1, and galectin-3, have been translated into clinical practice which offered significant improvement in the preoperative diagnosis of thyroid cancer." (PMID 22188859, 2011). "Some proteins' alteration was found in thyroid cancer, such as CK19, TG, Ki67, Calcitonin, TTF-1, BRAF, RET, HBME-1, SERPINA1, TfR1/CD71, FHL1 and galectin-3." (PMID 22188859, 2011). "Recently, the effect of a BRAF small inhibitory RNA construct and the BRAF kinase inhibitor AAL881 on both BRAF wild-type and mutant thyroid carcinoma cell lines was evaluated." (PMID 20628483, 2010).
thyroid cancer (continued). "However, our present findings indicate that papillary carcinoma with BRAF mutation, which comprises a considerable percentage of differentiated thyroid carcinomas, might not be the major origin of anaplastic carcinoma." (PMID 17453004, 2007). "CASTLE tumors demonstrated a higher median tumor mutational burden than thymic carcinoma and lacked the common BRAF and RAS mutations typically found in thyroid cancers." (PMID 42074143, 2026). "This decision paves the way for broader applications of this therapeutic strategy in BRAF-mutant thyroid cancers beyond ATC, including papillary and poorly differentiated thyroid carcinomas, which collectively account for a large proportion of BRAF-driven thyroid tumors." (PMID 41368991, 2025). "These expression patterns emphasize the potentially diverse roles that BRAF, TERT, and other genes may play in shaping the immune landscape of different thyroid cancer subtypes, potentially influencing immune evasion and response." (PMID 40450370, 2025). "A pilot study of 12 patients with BRAF V600E-mutant, RAI-refractory thyroid cancer demonstrated that 4 out of 10 evaluable patients exhibited increased iodine uptake on iodine-124 PET scans, leading to therapeutic I-131 administration and tumor regressions at 6 months." (PMID 41368991, 2025). "Dabrafenib (BRAF inhibitor) and Selumetinib (MEK inhibitor) have already demonstrated both tolerability and clinical activity in paediatric patients with solid tumours such as gliomas, neuroblastomas and thyroid cancers during phase I and II trials." (PMID 39671021, 2025). "Several studies have explored the PI3K–PTEN–AKT pathway as target for molecular therapy: double mutant BRAF p.V600E and PIK3CA thyroid carcinoma cells lines and xenograft models have heightened sensitivity to combination therapy with simultaneous MAPK and PI3K–PTEN-AKT pharmacological inhibition." (PMID 41175860, 2025). "Thirty percent of thyroid cancers will not carry any of the known mutations involved in thyroid cancer initiation and progression (RAS, RET/PTC, or BRAF (V600E) mutations)." (PMID 39218967, 2024). "Unlike some other cancers, like colorectal or thyroid cancer, where a single-point mutation (like KRAS rs#112445441 or BRAF V600E) is found in a large proportion of samples, in NMSC, there is no single mutation that is seen in a large number of samples." (PMID 38920684, 2024). "Mutations in BRAF, RET/PTC, NTRK1, or RAS have been reported in up to 70% of differentiated thyroid cancers and historically it does not depend on an MMR deficiency." (PMID 39062638, 2024). "In one of the largest series, six patients with ATC and two patients with poorly differentiated thyroid cancer (all at stage IVC and with BRAF wild-type) were treated with the L+P combination after surgical intervention, followed by EBRT and systemic chemotherapy." (PMID 39045273, 2024). "For these patients, the most common treatment options are represented by kinase inhibitor-based therapies that target different kinases, such as RET, BRAF, RAS, MAPK, and PI3K, constitutively activated in thyroid cancer cells as a consequence of specific genetic alterations." (PMID 39519020, 2024). "Additionally, efforts are being made to study and target genetic abnormalities such as BRAF and RET changes, which are frequent in thyroid cancer." (PMID 38501105, 2024). "Thus, the use of small molecular inhibitors targeting mutant BRAF and its downstream effector MEK has become a major therapeutic strategy for BRAF-mutant thyroid cancers." (PMID 38795180, 2024). "Lastly, BRAF and TERT assessments were conducted in a limited cohort, insufficient to represent the entire study population, and there is a paucity of data on the molecular characteristics and genetic information for thyroid cancer." (PMID 38711981, 2024). "The BRAF trial also included non-CNS tumors, such as thyroid cancer, biliary tract cancer, gastrointestinal cancer, and hematologic cancers." (PMID 39337916, 2024).
thyroid cancer (continued). "While some aspects of minority MOMP have been identified in mutant BRAF thyroid carcinoma, the role of Mcl-1 in this process is not well understood." (PMID 38622136, 2024). "Our data showed that STAG2 knockdown not only made BRAF-mutant thyroid cancer cells more dependent on glutamine rather than glucose, but also rendered them more sensitive to glutaminase inhibitor." (PMID 37479689, 2023). "Treatment with the BRAF inhibitor sorafenib partially prolongs progression-free survival in thyroid cancer patients, but fails to improve overall survival." (PMID 37803074, 2023). "Therefore, we conclude that the combination of BRAF V600 and HSP90 inhibition represents a novel and likely effective therapeutic option for patients with thyroid cancer, especially those that have failed previous treatments." (PMID 37803074, 2023). "In summary, the present study demonstrates that, although STAG2 inactivation activates ERK signaling, it does not affect cell proliferation and colony formation of BRAF-mutant thyroid cancer cells as well as their response to MEK inhibitor." (PMID 37479689, 2023). "However, in Nthy‐ori‐3.1 (BRAF WT) thyroid cells and FTC‐133 (BRAF WT) thyroid cancer cells, the endogenous BRAF WT protein was localized only in the cytoplasm and not in mitochondria." (PMID 35748101, 2022). "Treatment with sorafenib, the MEK inhibitor U0126 and the BRAF‐specific inhibitor PLX4720 did not change the mitochondrial localization or anti‐apoptotic activity of BRAF V600E in thyroid cancer." (PMID 35748101, 2022). "Although BRAF testing is widely available, there are no consistent data to support improvement in outcomes from incorporating it into therapeutic decision for thyroid cancer." (PMID 32972866, 2022). "RSPO4 protein and mRNA expression was decreased after BRAF knockout when compared to wild-type in our panel of metastatic and non-metastatic human thyroid cancer cell lines (THJ-16T, 8505C and TPC-1)." (PMID 36611933, 2022). "Studies have shown that the functional defect of DNA mismatch repair is most common in high mutation load thyroid cancer (46%), especially in ATC, and there is a lack of typical BRAF, RAS or RET thyroid oncogene mutations." (PMID 35865459, 2022). "In a study from Saudi Arabia, Sanger sequencing did not reveal BRAF V600E and TERT promoter mutations in the single case of pediatric PDTC evaluated as a part of a mixed cohort of pediatric thyroid cancers." (PMID 36553142, 2022). "Moreover, vemurafenib-treated BRAF V600E-positive PTC cells exhibited an increased apoptosis level, whereas ascorbic acid (vitamin C) was found to sensitize BRAF V600E-positive thyroid cancer cells to this agent." (PMID 34769260, 2021). "In addition, they found that DAC-induced NY-ESO-1 gene expression was reduced by the use of the BRAF inhibitor, PLX4720 in some BRAF mutant thyroid cancer cell lines." (PMID 34258030, 2021). "The BRAF V600E and the MAPK pathway was reported to activate several ETS transcription factors, the latter then selectively bonded to the mutant promoter of TERT and led to TERT activation in thyroid cancer." (PMID 34221969, 2021). "Similarly co-treatment of thyroid cancer cell lines with an EGFR inhibitor increased antitumor efficacy and suppressed resistance to the BRAF V600E inhibition." (PMID 34630336, 2021). "Mutations involving BRAF and TERT are important predictors of disease severity in thyroid cancer, but molecular testing is limited by cost and lack of adequate tissue sample." (PMID 34702207, 2021). "In thyroid cancer, phosphorylation and activation of ETS factor ELK1 by BRAF/MAPK pathway were necessary for thyroid-specific FOXE1 recruitment to TERT promoter via direct ELK1–FOXE1 interaction and this recruitment was independent from cis-acting mutations of TERT promoter." (PMID 34221969, 2021).
thyroid cancer (continued). "Gene mutations were found in the NRAS, KRAS, BRAF, and KIT genes and were similar to those in thyroid carcinoma, but some patients (37.5%) did not exhibit any gene mutations." (PMID 33763376, 2021). "In addition to these cancers, drivers of pancreatic cancers and thyroid cancers have been shown to exhibit KRAS (G12C, G12D) and BRAF (V599E) among MAPK pathways." (PMID 32260561, 2020). "Sanger sequencing of primary and metastatic tissues ruled out the presence of any mutations in known thyroid-cancer–related genes (H-, K-, N-RAS, BRAF, PTEN, PIK3CA), and PAX8-PPARG fusions were excluded by RT-PCR." (PMID 32674319, 2020). "In this context it was demonstrated that in mouse thyroid cancers with conditional BRAFV600E expression the lack of radioiodine incorporation depend on BRAF activity." (PMID 33198784, 2020). "Primary thyroid cancer TNM staging and pathologic diagnosis of UMs were not obtained in all cohort patients and BRAF mutation analyses on pathologic specimens were performed in only a few patients." (PMID 32841270, 2020). "For example, an immune score based on gene expression data was found to correlate significantly with recurrence-free survival in thyroid cancer patients, regardless of their BRAF(V600E) status." (PMID 31954372, 2020). "Even though results of direct comparison of dPCR and NGS in BRAF detection are not available in thyroid cancer it seems that dPCR can have a lower limit of detection compared to NGS in case of KRAS mutation." (PMID 31810221, 2019). "Thirdly, well-known thyroid cancer oncogenes, such as BRAF, were not available or adjusted in our study." (PMID 31523497, 2019). "Whether this BRAF-inhibitor also exerts a CXCL8-lowering effect,in thyroid cancer cells remains to be investigated." (PMID 30867499, 2019). "Importantly, Src appears to be a primary regulator of the PI3K pathway in BRAF-mutant and RAS-mutant thyroid cancer cell lines, which is consistent with a reduction in this pathway upon inhibition of Src or the combined inhibition of Src and MEK1/2." (PMID 29487290, 2018). "Therefore, we hypothesize that simultaneously suppressing BRAF V600E and ERK1/2 signaling could suppress the re-activation of ERK1/2 signaling by PLX4032, which may likely have a synergistic effect on thyroid gene expression and RAI uptake in thyroid cancer cells with BRAF V600E mutation." (PMID 30337961, 2018). "TERT promoter mutation, another potential marker of aggressive behavior in thyroid cancers, was also observed in HVPTC but not in CPTC, and was concurrent with BRAF V600E mutation." (PMID 28423545, 2017). "Interestingly, vascular invasion disappeared in tumors with WIPF1 knockdown as in tumors with BRAF V600E knockdown, providing functionally in vivo evidence for a role of WIPF1 in the invasiveness of thyroid cancer." (PMID 27863429, 2017). "Our findings lead us to speculate that combined therapy with BRAF and MEK inhibitors may be required for treatment of BRAFV600E mutant thyroid carcinoma." (PMID 28350298, 2017). "We show that RAS but not BRAF signals through ß-catenin and controls essential oncogenic functions in thyroid cancer cells." (PMID 27384483, 2016). "The aim of this work was to investigate whether the two main oncogenic drivers in thyroid cancer, RAS and BRAF, could activate the Wnt/ß-catenin pathway." (PMID 27384483, 2016). "Sorafenib was effective against all thyroid carcinoma cell lines regardless of their tumor subtype origin or BRAF status, confirming that sorafenib is therapeutically beneficial for patients with any subtype of dedifferentiated thyroid cancer." (PMID 25879531, 2015). "Absence of BRAF mutation and upregulated PI3K/AKT pathway in canine thyroid cancers suggest that activation of PI3K/AKT pathway, rather than MAPK pathway, plays a more important role for the tumorigenesis of FTC and MTC." (PMID 29061943, 2015).
thyroid cancer (continued). "Therefore, in this study we used rat thyroid cells as a model to study the impact of BRAF V600E/MAPK on histone acetylation of NIS and found similar NIS promoter deacetylation patterns in rat thyroid cells and human thyroid cancer cells." (PMID 24243688, 2014). "Inhibition of either oncogenic BRAF or SRC has marked anti-tumor effects in mouse models of thyroid cancer, however, neither drug induces notable apoptosis." (PMID 24994118, 2014). "Notably, thyroid cancers have the highest frequency of recurrent kinase fusions (63/498, 13%), and all fusion events including ALK, BRAF, MET, NTRK1, NTRK2, RAF1 and RET are mutually exclusive in this cancer type." (PMID 25204415, 2014). "In human thyroid carcinomas, constitutive signaling of the MAP kinase cascade contributes to the development of thyroid cancer promoted by activated RAS and BRAF onco-proteins and that this occurs, at least in part, by compromising the Skp2-dependent degradation pathway." (PMID 21386910, 2011). "We have shown that in thyroid cancer cells sorafenib induces apoptosis by affecting Mcl-1 and Bcl-2 in BRAFV600E mutated cells which was independent of BRAF." (PMID 19878585, 2009). "Our results also show that p27Kip1 and cyclin D1 proteins are important in the regulation of proliferation via BRAFV600E-ERK signalling and BRAF does not seem to be a major protein for the survival of thyroid cancer cells." (PMID 19878585, 2009). "Because current therapeutic options for patients with thyroid cancers that are aggressive and/or do not respond to standard therapies are limited, BRAF and its downstream effectors represent attractive therapeutic targets." (PMID 17179987, 2007). "Whether enhanced RAF kinase activity influences these later changes is an uncertain but important question when considering BRAF and RAF kinases as therapeutic targets for patients with undifferentiated forms of thyroid cancer." (PMID 17179987, 2007). "In addition, we established BRAFV600E-driven transgenic mouse model of thyroid cancer (TPO-Cre/LSL-BrafCA) and demonstrated that Ng2 was significantly increased in tumor tissues from BRAF-mutant mice (BRAFV600E) compared with wild-type ones (BRAFWT) by qRT-PCR and immunofluorescence (IF) assays." (PMID 38795180, 2024). "That being said, additional studies with larger sample sizes comparing BRAF V600E-mutant thyroid cancer cases among Hispanics and non-Hispanics are merited to better characterize the effect of BRAF V600E on the prevalence of advanced features and mortality risk." (PMID 38539437, 2024). "Immunohistochemical analysis indicated a negative BRAF (V600E) status in the thyroid cancer cells." (PMID 39558959, 2024). "Nevertheless, the negative immunoreactivity for BRAF V600E in all cases indicates that the combination of morphological analysis with immunohistochemistry may improve the prediction for thyroid carcinoma harboring the RET and/or NTRK fusion genes." (PMID 38472412, 2024). "However, because advanced recurrent thyroid cancer is relatively rare, there is no concomitant diagnosis of thyroid cancer or treatment targeting BRAF under the current Japanese insurance system." (PMID 36251535, 2023). "Furthermore, Notarangelo and colleagues reported that the exposure of thyroid cancer cells to vemurafenib resulted in a rapid feedback activation of EGFR pathway, and dual EGFR and BRAF blockade induces suppression of ERK signaling, inhibition of cell proliferation, and synthetic lethality." (PMID 36624452, 2023). "Statistical analysis of the LFC profiles with the BRAF V600E-specific inhibitor dabrafenib differentiated BRAF V600E and non-BRAF V600E thyroid cancers, with six peptides (BAD_93- 105, CD27_212-224, MPIP1_172-184, PRKDC_2618-2630, and RB_242-254) showing p < 0.05." (PMID 37760447, 2023).